ASF1A (anti-silencing function 1A histone chaperone)
Diseases named in the same sentence as ASF1A in open-access papers (continued):
Sharing a sentence is not in itself a finding about the gene and the disease.
cancer (14 papers, 2011 to 2025). A tumor composed of atypical neoplastic, often pleomorphic cells that invade other tissues. "ASF1A is highly expressed in prostate cancer cells, and its overexpression is associated with poor prognosis in cancer patients." (PMID 35372800, 2021). "In the present study, we determine whether ASF1a is required for the unlimited proliferation of cancer cells, a key cancer hallmark." (PMID 30692519, 2019). "We hypothesize that SETD2-deficient cancer may be more sensitive to the inactivation of ASF1A and ASF1B than SETD2-proficient cancer if SETD2 loss–induced increase in histone exchange is required for creating a permissive epigenetic landscape to enhance oncogenic transcriptional output." (PMID 36810256, 2023). "ASF1A is one of E2F targets predicted to repress cancer immunity and was identified as a critical regulator of sensitivity to anti–PD-1 therapy in LUAD." (PMID 36304306, 2022). "ASF1A is specifically required for H3K56ac by cooperating with histone acetyltransferase p300, and H3K56ac is increased in multiple types of cancer, correlating with increased ASF1A expression." (PMID 36184659, 2022). "For example, knockout ASF1A leads to the introduction of DSBs, which sensitizes cancer cells to radiotherapy, chemotherapy, and immunotherapy." (PMID 35372800, 2021). "Regarding several cancer cases, ASF1A accumulation is a general characteristic that occurs in tumorigenesis." (PMID 35372800, 2021). "In summary, our findings indicate ASF1a as a crucial oncogenic factor aberrantly overexpressed in a variety of cancers." (PMID 30692519, 2019). "The overexpression of ASF1a was similarly found in 20 cancer types contained in TCGA and GTEx datasets." (PMID 30692519, 2019). "Histone chaperone ASF1A is often dysregulated in cancers, however the regulation of its abundance is unclear." (PMID 29599486, 2018). "Immunohistochemical staining showed an upregulation of both USP52 and ASF1A in carcinomas derived from breast, kidney, and rectum within at least two of three paired samples." (PMID 29599486, 2018). "ASF1A accumulated in cancer cell lines with downregulated RAD6 levels, although the MDM2 levels were upregulated." (PMID 26336826, 2015). "In addition, several studies found that ASF1A was overexpressed in human malignancies which was necessary for the proliferation of cancer cells." (PMID 36861063, 2023). "Some reports have shown that blocking the expression of ASF1A by RNA interference, small inhibitors, and chemotherapy drugs can effectively inhibit the proliferation and growth of tumors and improve the sensitivity to anti-cancer drugs and immunotherapy." (PMID 35372800, 2021). "In the present study, we explored the role of ASF1a in the immortal phenotype of cancer cells." (PMID 30692519, 2019). "The results support the concept that ASF1a is a potential novel target in cancer treatment." (PMID 30692519, 2019).
cancer (continued). "Moreover, higher ASF1a expression and lower p21cip1 expression predict a poor outcome in HCC patients, indicating the potential value of ASF1a in cancer as a prognostic biomarker and therapeutic target." (PMID 30692519, 2019). "It has been reported that ASF1A and H3K56Ac levels are elevated in many different cancer tissues." (PMID 26336826, 2015). "ASF1A may also serve as a potential target in cancer therapy." (PMID 36861063, 2023). "Thus, ASF1a may serve as a potential target in cancer therapy." (PMID 30692519, 2019). "ASF1a interacts with the transcription factor β-catenin and activates the downstream genes cyclin D1, myc, Lgr5, and ZEB1, promoting cancer development and progression." (PMID 30692519, 2019). "Additionally, the CNV condition and expression level of ASF1A, CDKN2A, MAGOHB, NADK, SPOP, and ARC were remarkably correlated in most cancer types." (PMID 37497116, 2023). "Recently, ASF1a has been shown to be up-regulated in certain human malignancies and required for the expression of telomerase reverse transcriptase (TERT), a factor essential for the immortal phenotype of cancer cells; however, its role in oncogenesis remains poorly defined." (PMID 30692519, 2019). "Three genes ASF1A, RASGRP3 and ZNF24 were not covered by any representative term and none of them is an NCG cancer gene." (PMID 34504716, 2021).
infection (3 papers, 2018 to 2021). The state of being infected such as from the introduction of a foreign agent such as serum, vaccine, antigenic substance or organism. "HIRA and an upstream H3 chaperone, ASF1A, have been implicated in H3.3-biased occupation of histones on HSV DNA during lytic infection of HeLa cells." (PMID 33909709, 2021). "When transcription was inhibited globally, we found that only a combinatorial depletion of ATRX/HIRA/ASF1A resulted in a significant decrease in total H3 deposition by 4 h post infection (hpi), suggesting multiple pathways for chromatinizing naked DNA." (PMID 33909709, 2021). "Previous studies have reported that HIRA and ASF1A promote H3.3 and total H3 occupation, respectively, on the HSV genome during early lytic infection in HeLa cells." (PMID 33909709, 2021). "This is supported by reports that HIRA and ASF1A promote histone occupation on HSV DNA during the first few hours of infection but do not appear to be restrictive during this same period of time." (PMID 30465651, 2018). "Two members of the HIRA complex, HIRA and ASF1a, were previously shown to be involved in H3.3-dependent chromatinization of HSV-1 genomes at early times after infection in non-neuronal and non-primary cells favoring the onset of the lytic cycle." (PMID 30235352, 2018).
neurological disease (1 paper, 2025). "Ten proteins showed co-localization with a neurological disease using both plasma protein abundance and plasma mRNA abundance (SIRPA, CTSH and CD33 with AD; and ASF1A, FCRL3, VEGFB, TYMP, PVALB, LMAN2 and CD5 with MS)." (PMID 40037332, 2025).
ASF1A also shares sentences with these, for which no sentence is quoted: breast (1 paper); cervical cancer (1); chronic myeloid leukemia (1); gastric cancer (1); pancreatic cancer (1); psoriasis (1); rectum (1); thyroid carcinoma (1).